PON1 (paraoxonase 1)
Diseases named in the same sentence as PON1 in open-access papers (continued):
Sharing a sentence is not in itself a finding about the gene and the disease.
Arthritis (4 papers, 2020 to 2024). Inflammation of a joint. "Arthritis activity in K/BxN mice at 21 weeks was associated with reduction in serum PON1 activity and impaired HDL function." (PMID 33033318, 2020). "Moreover, higher PON1 activity was associated with lower arthritis activity in both RA patients and in a mouse model of RA, and overexpression of the human PON1 transgene in mice was associated with reduced inflammatory arthritis." (PMID 37899440, 2023). "PON1 is not only associated with CVD in arthritis but may also dampen inflammation as shown in PON1-transgenic mice." (PMID 34680168, 2021). "PON1 activity was markedly decreased, and multiple BLM were elevated in association with arthritis activity." (PMID 33033318, 2020). "Overexpression of the human PON1 transgene prevented increases in multiple BLM following arthritis induction and reduced both clinical and histologic arthritic disease." (PMID 33033318, 2020). "K/BxN serum transfer (STIA) or collagen antibody transfer (CAIA) was used for arthritis induction in B6 mice homozygous for the PON1 human transgene [PON1Tg], PON1 knock-out mice [PON1KO], and wild type littermate control mice [WT]." (PMID 33033318, 2020). "It is possible that the intensity of inflammation prevented sufficient “potential” to observe further worsening of arthritis with KO of the PON1 gene." (PMID 33033318, 2020). "Regarding the impact of protein intake, there is little evidence identifying only one study in which the decrease in PON1 activity (specifically in rats induced by arthritis) was restored after treatment with soy protein and isoflavones (genistein and daidzein)." (PMID 39199265, 2024). "We hypothesized that knock out of the PON1 gene would result in more severe arthritic disease following arthritis induction." (PMID 33033318, 2020). "Higher serum PON1 activity correlated significantly with lower clinical arthritis scores." (PMID 33033318, 2020). "Higher serum PON1 activity correlated with lower BLM and lower arthritis activity in both K/BxN mice and RA patients." (PMID 33033318, 2020). "PON1 KO mice did not have worsened arthritis following induction with K/BxN serum or collagen antibody transfer." (PMID 33033318, 2020).
cerebral infarction (4 papers, 2018 to 2022). An ischemic condition of the brain, producing a persistent focal neurological deficit in the area of distribution of the cerebral arteries. "Changes of MDA, ROS, TBARS, AOPP, SOD 1, SOD 2, SOD 3, and PON 1 indicated an increase in the severity of concomitant brain infarcts and coronary occlusions in patients." (PMID 35801004, 2022). "Here, in the studied group consisting of 152 patients with confirmed cerebral infarction, the PON1 methylation level was significantly higher than in the 152 healthy individuals who served as the control group." (PMID 33670025, 2021). "In this study where Mexican subjects were included, Q192R and L55M polymorphisms, paraoxonase and arilesterase activities from PON1 are not risk factors for atherothrombotic cerebral infarction." (PMID 30410197, 2018).
diabetic retinopathy (4 papers, 2013 to 2024). "Regarding the associations of PON1 with microvascular late complications, in our study sample, the presence of PON1 rs622 GG genotype also posed a higher risk of diabetic retinopathy." (PMID 38084238, 2023). "Many studies have found associations between PON1 polymorphisms and diabetic retinopathy." (PMID 23441121, 2013). "However another study observed an association between diabetic retinopathy and PON1 rs854560, but not PON1 rs622." (PMID 38084238, 2023).
gastric cancer (4 papers, 2014 to 2020). A primary or metastatic malignant neoplasm involving the stomach. "Some studies have indicated a link among the PON1 activity, gastric cancer susceptibility, and patients’ OS." (PMID 25545243, 2014). "In detail, a Glu to Arg change at the codon 192 from an A to G substitution in rs662 is correlated with increased PON1 activity, suggesting a potential link between rs662 and gastric cancer." (PMID 25545243, 2014). "Atay reported that the PON1 activity is an independent predictor of OS for patients with gastric cancer (both metastatic and nonmetastatic)." (PMID 25545243, 2014).
left ventricular hypertrophy (4 papers, 2019 to 2024). Enlargement of the LEFT VENTRICLE of the heart. "A study in CKD patients with cardiomyopathy reported that the severity of left ventricular hypertrophy and left ventricular dysfunction correlates in a dose dependent manner with the R allele in the PON-1 polymorphism Q192R." (PMID 31311140, 2019). "Our data suggest that a loss of PON-1 in the salt-sensitive hypertensive model of CKD leads to increased cardiac inflammation and fibrosis as well as a molecular and functional cardiac phenotype consistent with compensated left ventricular hypertrophy." (PMID 36140402, 2022).
lipid metabolism disorder (4 papers, 2013 to 2025). "The paraoxonase activity of the PON-1 enzyme is one of the most extensively studied in diseases associated with increased oxidative stress, inflammation, and lipid metabolism disorder." (PMID 40002395, 2025). "There is a need for further studies in this field to clearly determine the influence of SNPs in the PON1 gene on the risk of diseases associated with lipid metabolism disorders." (PMID 39684839, 2024). "Moreover, in this paper, we described the changes in the structure of PON1 induced by genetics and environmental factors and their association with the risk of disease based on lipid metabolism disorders." (PMID 39684839, 2024). "The observed rise in glycosylated PON1 in HCC might be attributed to the upregulation of corresponding glycosyl transferases, potentially linked to cancer-induced lipid metabolism disorder and a potential impairment in the anti-lipid peroxidase and anti-oxi radical abilities of PON1." (PMID 37908943, 2023). "Recent studies have demonstrated that lipid metabolism disorder may play a vital role in pathogenesis of ONFH and mutation of the paraoxonase-1 (PON-1) gene may be involved in the occurrence of this disease." (PMID 24206655, 2013).
peripheral artery disease (4 papers, 2011 to 2024). "Our research group has paid special attention to investigating the potential utility of CCl2, PON1, and associated metabolic alterations as markers in the diagnosis of peripheral arterial disease (PAD) of the lower extremities." (PMID 34356595, 2021).
rectal cancer (4 papers, 2021 to 2025). A primary or metastatic malignant neoplasm that affects the rectum. "It was reported that PON1 was associated with oxidative stress status and resistance to neoadjuvant chemoradiotherapy in patients with rectal cancer." (PMID 40404896, 2025). "On the other hand, among DEP upregulated in exosomes of good responders was PON1, an important antioxidant enzyme, which elevated serum level was previously observed in rectal cancer patients in response to neoadjuvant radiochemotherapy." (PMID 35205741, 2022). "We report a pilot study on the feasibility of determinations of circulating levels of paraoxonase-1 (PON1) and compounds related to energy metabolism as biomarkers for the evaluation of patients with rectal cancer (RC), and the effects produced by neoadjuvant radiochemotherapy (NRCT)." (PMID 33886674, 2021).
steatosis (4 papers, 2010 to 2024). Increased lipid within the cytoplasm of cells. "Nevertheless, correlations were found between certain PON1-related variables, steatosis, and ballooning." (PMID 38136158, 2023). "This protein was identified as glycosylated PON1 and was also present in biopsies from patients with steatosis and from rats with CCl4-induced hepatic impairment." (PMID 20470383, 2010). "PON1 is known to attenuate oxidative stress, which is augmented during steatosis progression." (PMID 27642496, 2016). "Moreover, hepatic PON1 activity was negatively correlated with the amount of total fat extracted from the liver (r = −0.48, p < 0.001) and serum PON1 activity was negatively correlated with the degree of steatosis (r = −0.60, p < 0.0001)." (PMID 27642496, 2016). "We also found a negative correlation between serum PON1 activity and progression of steatosis in rats receiving açai pulp." (PMID 27642496, 2016).
uremia (4 papers, 2013 to 2021). A clinical syndrome associated with the retention of renal waste products or uremic toxins in the blood. "Therefore, PON1 SNV associations with HCV clearance could be negatively influenced by uremia." (PMID 34445971, 2021). "The uremic milieu of dialyzed individuals might influence the transcription and translation of PON1 SNVs, probably downregulate, as serum PON-1 activity and concentration are usually decreased in uremia." (PMID 34445971, 2021). "For example, patients with high atherosclerotic vascular disease risks, such as smokers, exhibit lower HDL PON-1 mass and activity than those with low risks, such as nonsmokers; moreover, uremia patients have lower LCAT levels and activities than patients without uremia." (PMID 26090384, 2015).
autism spectrum disorder (3 papers, 2010 to 2020). A spectrum of developmental disorders that includes autism, and Asperger syndrome. "In addition, PON1 polymorphisms and enzyme activities have been associated with autism spectrum disorder." (PMID 21126941, 2010). "Although an association between autism spectrum disorder (ASD) and the R variant of the PON1 Q192R SNP and between the L variant of SNP L55M, was published, other studies in Europe and in North America did not replicate these findings." (PMID 32976529, 2020).
bladder cancer (3 papers, 2015 to 2026). "This study provides initial evidence of intratumoral PON1 expression in bladder cancer and suggests that combined PON1/MTAP immunohistochemical assessment may reflect tumor grade and biological behavior." (PMID 41750579, 2026).
cerebral atherosclerosis (3 papers, 2014 to 2022). Atherosclerosis of the cerebral vasculature. "PON 1 activity as an antiatherogenic factor prevents oxidative modification of low-density lipoprotein and plays an important role in inhibiting the development of cerebral atherosclerosis." (PMID 35801004, 2022).
colon carcinoma (3 papers, 2006 to 2021). "Our data report a number of significant findings: First, in our case-control study, PON1 arylesterase and lactonase activities are lower in colon cancer patients confirming the effect of cancer itself and/or of added chronic inflammation as previously shown." (PMID 31234489, 2019). "We also compared PON1 activity between colon cancer patients and age and gender-matched control subjects." (PMID 31234489, 2019).
diabetic neuropathy (3 papers, 2007 to 2021). A chronic, pathological complication associated with diabetes mellitus, where nerve damages are incurred due to diabetic microvascular injury involving small blood vessels that supply these nerves, resulting in peripheral and/or autonomic nerve dysfunction. "Although microangiopathy plays a role in the pathogenesis of diabetic neuropathy, there has been little research on PON-1 activity in patients with DM." (PMID 22291696, 2012). "To assess the effects of a PR-enriched diet on the development of diabetic neuropathy, we also evaluated the effect of PR- and BR-enriched diets on serum PON1 activities in STZ-induced diabetic rats." (PMID 18036220, 2007).
end-stage renal disease (3 papers, 2012 to 2021). "Previous studies have shown that PON1 activity is lower in patients with chronic inflammation, such as in end stage renal failure." (PMID 31234489, 2019).
endotoxemia (3 papers, 2016 to 2023). "This is the first study reporting PON-1 activity in horses with ongoing endotoxemia caused by experimental LPS administration." (PMID 33148245, 2020). "The hypothesis of the study was that oxidative phenomena associated with endotoxemia may induce a decrease of PON-1 activity that parallels the other changes detected after LPS administration." (PMID 33148245, 2020). "Our data seem to state that endotoxemia triggers changes in PON-1 activity later and for a longer period, compared with leukocyte count and plasma iron concentration." (PMID 33148245, 2020). "The objective of the study was to investigate the behaviour of PON-1 in horses after experimentally induced endotoxemia." (PMID 33148245, 2020). "The aim of the study was to investigate the behaviour of plasma PON-1 activity from horses with experimentally induced endotoxemia included in a previous study, on which the administration of LPS induced evident haematological and biochemical changes consistent with inflammation." (PMID 33148245, 2020). "The results of this study suggest that measurement and monitoring of PON-1 activity might be useful to evaluate progression and recovery from endotoxemia in horses." (PMID 33148245, 2020). "Therefore, further studies are warranted to investigate changes in PON-1 activity during natural onset of endotoxemia in horses." (PMID 33148245, 2020). "These and our results seem to state that experimentally induced endotoxemia induces changes in PON-1 activity that does not have a rapid resolution, contrarily to clinical signs, that normalize earlier." (PMID 33148245, 2020). "Endotoxemia studies in dogs showed that these beneficial effects of choline treatment might be related with inhibition of TNF-α synthesis, prevention of hepato-renal injury, and attenuation of the changes of serum butrylcholinesterase and paraoxonase-1 activities." (PMID 27646125, 2016).
gestational diabetes mellitus (3 papers, 2020 to 2023). "In gestational diabetes mellitus (GDM) patients, CEC of maternal GDM-HDL is 25% lower than that of healthy HDL, which is found to be positively correlated with the PON1 activity and contens of APOA1 and APOE." (PMID 37386457, 2023).
HIV-1 infection (3 papers, 2014 to 2025). The type species of lentivirus and the etiologic agent of acquired immunodeficiency syndrome (AIDS). "Based on the results described, the odds ratio (OR) of the susceptibility to HIV-1 infection in relation to polymorphisms of the PON-1 and PON-2 genes was calculated using univariate binary logistic regression." (PMID 40002395, 2025). "Additionally, it is important to explore the molecular and pathophysiological mechanisms underlying HIV-1 infection and the role of PON-1 and PON-2 polymorphisms, along with their enzyme activities, to reduce oxidative stress in PLWH." (PMID 40002395, 2025). "This is the first time that the L55M PON-1 polymorphism has been associated with HIV-1 infection." (PMID 40002395, 2025). "Therefore, the results described here and in other studies suggest the prevalence of alterations in lipid metabolism in individuals who are seropositive for HIV-1 who have been treated with PI, as well as changes in the activity of the PON1 enzyme that are associated with HIV-1 infection." (PMID 24719500, 2014). "To determine whether polymorphisms in the PON-1 and PON-2 genes, along with paraoxonase activity, are associated with HIV-1 infection in PLWH, we conducted a sex-matched case-control study." (PMID 40002395, 2025). "Some studies have shown that the activity of PON1 may be affected and/or inactivated by oxidative stress, which could explain its reduced activity during HIV-1 infection." (PMID 24719500, 2014). "Therefore, the existence of a relationship between the number of CD4+ T-cells and PON1 activity, which would be directly related to the best course of HIV-1 infection, may be suggested." (PMID 24719500, 2014). "Moreover, there is an interaction between the polymorphism and HIV-1 infection, regardless of the ART treatment stage, that increases the PON-1 paraoxonase activity (p < 0.001)." (PMID 40002395, 2025).
hypertensive renal disease (3 papers, 2022 to 2024). "Control Dahl salt-sensitive rats (SS-wild) along with Pon1 mutant rats (SS-PON1 KO rats) were maintained on a high-salt diet (8% NaCl) to initiate the salt-sensitive hypertensive renal disease that is characteristic of this model." (PMID 35624764, 2022). "We investigated the hypothesis that PON-1 is cardioprotective in a Dahl salt-sensitive model of hypertensive renal disease." (PMID 36140402, 2022). "First, to examine the renal protective role of PON-1 in settings of CKD, ten-week-old, age-matched male rats were maintained on a high-salt diet (8% NaCl) for up to 5 weeks to initiate the salt-sensitive hypertensive renal disease characteristic of this model." (PMID 35624764, 2022).
inflammatory bowel disease (3 papers, 2019 to 2024). A spectrum of small and large bowel inflammatory diseases of unknown etiology. "PON1 activity is reduced in inflammatory bowel disease, reflecting its activity and inflammation severity." (PMID 38398809, 2024).
lymph node metastasis (3 papers, 2017 to 2022). "PON1 was found to downregulate in gastroesophageal cancers and associated with lymph node metastasis." (PMID 35711939, 2022). "In our examination of whether PON1 L55M or Q192R polymorphism genotype frequencies were associated with clinicopathological parameters in BC patients, we found that the PON1-55M allele was associated with postmenopausal status and lymph node metastases." (PMID 28445984, 2017). "The reduction of PON1 appeared to present with lymph node metastasis, whereas PON1 failed to serve as an independent indicator for clinical application." (PMID 35372408, 2022).
lymphoma (3 papers, 2013 to 2025). A malignant (clonal) proliferation of B- lymphocytes or T- lymphocytes which involves the lymph nodes, bone marrow and/or extranodal sites. "In contrast, we observed that rs662 in PON1 was associated with lymphoma risk, being the GG genotype related with increased susceptibility to lymphoma in general, and to FL and DLBCL in particular." (PMID 23651475, 2013). "This is the first study demonstrating a relationship between the germline rs662 PON1 polymorphism and lymphoma risk although this finding should be confirmed in larger and independent series." (PMID 23651475, 2013). "PON-1 was significantly lower in round-cell mesenchymal neoplasms, with lymphoma and mast cell tumor being the more common tumors in this category." (PMID 40559770, 2025). "PON-1 was significantly lower in round-cell mesenchymal neoplasms, mostly represented by lymphoma and mast cell tumor, compared to epithelial and spindle-cell mesenchymal neoplasms (p = 0.049)." (PMID 40559770, 2025). "We have studied the prevalence of three functional polymorphisms affecting these genes rs1051740 EPHX1, rs1800566 NQO1 and rs662 PON1 in 215 patients with lymphoma and 214 healthy controls." (PMID 23651475, 2013). "This analysis revealed that the combination of the PON1, EPHX1 and NQO1 polymorphisms did not increase the lymphoma risk associated with the PON1 polymorphism alone (OR = 1.7 vs. 1.5)." (PMID 23651475, 2013).
meningioma (3 papers, 2007 to 2023). A generally slow growing tumor attached to the dura mater. "One study assessed the risk of developing astrocytomas and meningiomas because of PON-1 polymorphisms." (PMID 37108044, 2023). "A total of 71 cases, 43 with astrocytoma and 28 with meningioma, were compared to 220 healthy control samples for frequency of the PON-1 variants L55M and Q192R." (PMID 37108044, 2023). "For meningioma patients the results for association tests for the PON1 L55M polymorphism were as follows: Genotypic test, p = 0.605; trend test, p = 0.386, dominant model, p = 0.605, recessive model p = 0.323." (PMID 20723250, 2010). "However, a few studies have investigated the causative association between PON-1, astrocytomas, and meningiomas." (PMID 37108044, 2023). "The minor allele frequencies were as follows: PON1 55L, 0.398, 0.328 and 0.286 for patients with astrocytoma, meningioma and control individuals, respectively; PON1 192R, 0.341, 0.362 and 0.302 for patients with astrocytoma, meningioma and control individuals, respectively." (PMID 20723250, 2010). "Common nonsynonymous PON1 polymorphisms are not related with the risk of developing astrocytoma and meningioma." (PMID 20723250, 2010).